WEE1 (WEE1 G2 checkpoint kinase)
Diseases named in the same sentence as WEE1 in open-access papers (continued):
Sharing a sentence is not in itself a finding about the gene and the disease.
vulvar squamous cell carcinoma (4 papers, 2013 to 2024). An invasive squamous cell carcinoma arising from the vulva. "Based on its association with malignancy in vulvar carcinoma samples, we shut down the expression of Wee1 in two vulva squamous cell carcinoma cell lines, SW-954 and CAL-39." (PMID 23767999, 2013). "In addition, Magnussen and colleagues showed a correlation between high WEE1 expression and vulvar squamous cell carcinoma prevalence in younger patients." (PMID 27418131, 2016). "In the present study we show for the first time that Wee1 is expressed at a higher level in vulvar squamous cell carcinomas compared to normal tissue, and that high expression of the kinase correlates with malignant features including poor histological differentiation and lymph node metastases." (PMID 23767999, 2013).
adenoma (3 papers, 2022 to 2025). A neoplasm arising from the epithelium. "Several of the genes encoding kinase presented isoforms, resulting from alternative splicing of mRNA: kinases PAK7 and STK26 in NR5A1-derived tumors, kinase PPIP5K2 in POU1F-derived adenomas and kinases like PPIP5K2 and kinases WEE1 and STK17 in the TBX19 tumors." (PMID 35260162, 2022).
brain cancer (3 papers, 2019 to 2026). A primary or metastatic malignant neoplasm affecting the brain.
diffuse large B-cell lymphoma (3 papers, 2019 to 2024). "The cell cycle checkpoint protein WEE1 is highly expressed in genomically unstable cancers, including diffuse large B-cell lymphoma (DLBCL)." (PMID 31703356, 2019).
metastatic colorectal cancer (3 papers, 2020 to 2022).
pancreatic adenocarcinoma (3 papers, 2015 to 2022). "Similarly, MiaPaCa2 (pancreatic adenocarcinoma) cells were found to be sensitized towards gemcitabine upon inhibition of Wee1 or ATR." (PMID 25965828, 2015).
Telangiectasia (3 papers, 2021 to 2025). Telangiectasias refer to small dilated blood vessels located near the surface of the skin or mucous membranes, measuring between 0.5 and 1 millimeter in diameter. "On the other hand, as already shown, alterations in non-BRCA1/2 HRR genes may confer sensitivity not only to PARP inhibitors but also to the WEE1 checkpoint inhibitor or the ataxia telangiectasia and Rad3-related protein inhibitor." (PMID 33800556, 2021).
anaplastic thyroid cancer (2 papers, 2021 to 2025). "Conversely, excessive iodine intake may contribute to the development of papillary and anaplastic thyroid cancer by activating the AKT/Wee1/CDK1 signaling pathway, which accelerates the cell cycle and may contribute carcinogenesis." (PMID 41228194, 2025). "Furthermore, activating AKT/Wee1/CDK1 axis was involved in the proliferation of papillary and anaplastic thyroid cancer cells induced by high iodine." (PMID 33796458, 2021).
chronic hepatitis (2 papers, 2009 to 2012). An active inflammatory process affecting the liver for more than six months. "Previously, protein levels and kinase activities of cyclin D1, E, Cdk4, cyclin A, and Wee1 were demonstrated to increase proportionally with the development of HCC, especially in the transition process from chronic hepatitis to HCC." (PMID 22539975, 2012). "In another in vitro study protein levels and activities of cyclin D1, E, Cdk4, cyclin A and Wee1 increased proportionally with the development of HCC, especially in the transition process from chronic hepatitis to HCC." (PMID 27942274, 2009).
diffuse intrinsic pontine glioma (2 papers, 2022). A neuroglial tumor that arises from the middle portion of the brain stem. "WEE1 was found to be highly expressed in diffuse intrinsic pontine glioma (DIPG; now known as diffuse midline glioma) and in pediatric high-grade gliomas (HGGs)." (PMID 35158967, 2022).
hyperlipidemia (2 papers, 2014 to 2025). "One unanswered question arising from our study is how oxLDL/hyperlipidemia induces WEE1 phosphorylation or self‐phosphorylation in macrophages." (PMID 40202104, 2025). "WEE1 deletion also inhibited p65 activation in MPMs challenged by mouse serum with hyperlipidemia." (PMID 40202104, 2025). "Besides oxLDL stimulation, we harvested the HFD‐fed mouse serum including hyperlipidemia to treat MPMs and found that WEE1 deletion inhibited hyperlipidemia‐induced TNF‐α and IL‐6 levels in cultured MPMs." (PMID 40202104, 2025).
laryngeal carcinoma (2 papers, 2018 to 2020). Carcinoma that arises from the laryngeal epithelium. "SNHG3 can modulate the cell growth and migration of laryngeal carcinoma by modulating miR‐384/WEE1 pathway." (PMID 32248648, 2020). "MiR-503 might decrease the radioresistance of laryngeal cancer cells via the inhibition of WEE1." (PMID 29930482, 2018).
mesothelioma (2 papers, 2019 to 2024). A usually malignant and aggressive neoplasm of the mesothelium which is often associated with exposure to asbestos. "WEE1 inhibitors have been developed to target various types of cancer, including advanced solid tumors, such as ovarian, endometrial, mesothelioma, breast, colon, pancreatic, and NSCLC." (PMID 38776912, 2024).
nematode infection (2 papers, 2018 to 2024). "WEE1 may also be involved in DNA checkpoint control in Arabidopsis during nematode infection." (PMID 39974374, 2024).
prostate tumor (2 papers, 2017 to 2023). "To fully exploit the therapeutic potential of WEE1 inhibition, we further examined the effectiveness of AZD1775 in a mouse survival experiment, in which treatment was initiated upon the development of palpable primary prostate tumors and continued until death or humane moribund endpoints." (PMID 37987002, 2023).
retinoblastoma (2 papers, 2021). A malignant tumor that originates in the nuclear layer of the retina. "As shown in the protein network plot for retinoblastoma-related genes, SMC2, HMGB1, WEE1, RRM2, and POLA1 proteins showed an association with other proteins." (PMID 34646884, 2021). "The STRING database plotted their protein network, and the five proteins WEE1, SMC2, HMGB1, RRM2, and POLA1 that were most associated with the range of activity involved in tumorigenesis and retinoblastoma progression were selected from 366 genes." (PMID 34646884, 2021).
serous carcinoma (2 papers, 2015 to 2025). "Furthermore, combining poly (ADP-ribose) polymerase (PARP) and WEE1 inhibitors has shown promising activity in p53abn/CCNE1-amplified serous carcinomas, targeting the specific DNA damage response vulnerabilities created by these alterations." (PMID 40940815, 2025).
vulvar carcinoma (2 papers, 2013 to 2021). "Further on, high nuclear expression of Wee1 was associated with high nuclear levels of the S-phase specific Cyclin A protein in vulvar carcinoma samples." (PMID 23767999, 2013). "In our present study, we did not observe any significant association between disease-specific survival and Wee1 expression for patients with vulvar carcinomas." (PMID 23767999, 2013). "In the present study our aim was to determine Wee1 expression in vulvar cancer, if it had an association with known clinicopatological variables and biomarkers, and finally if in vitro targeting of the kinase may be beneficial as mono-therapy." (PMID 23767999, 2013). "The association between Wee1 and Cyclin A in vulvar cancer could therefore simply be due to both proteins being expressed in S-phase." (PMID 23767999, 2013). "The fact that increased expression of Wee1 was associated with lymph node metastasis and poor tumor differentiation indicate that high level of Wee1 may be involved in malignant progression of vulvar carcinomas." (PMID 23767999, 2013). "The association between high expression of Wee1 and malignant features in vulvar tumors spurred us to explore how silencing Wee1 would affect the two vulvar cancer cell lines; SW-954 and CAL-39." (PMID 23767999, 2013). "Our in vitro results showed that siRNA mediated Wee1 silencing only led to a modest reduction in viability, when examined in vulvar cancer cell lines." (PMID 23767999, 2013). "Our results suggest that Wee1 may be involved in the progression of vulvar carcinomas." (PMID 23767999, 2013). "Thus, it is possible that Wee1 has a protective function in vulvar carcinomas." (PMID 23767999, 2013). "In the vulvar carcinoma cell lines SW-954 and CAL-39 high levels (score ≥6) of nuclear Wee1 immunostaining were observed, additionally, cytoplasmic staining (score =2) was observed in SW-954 cells." (PMID 23767999, 2013).
clear cell renal cell carcinoma (1 paper, 2024). "We sought to evaluate the efficacy of WEE1 inhibitor adavosertib in patients with solid tumor malignancies (cohort A) and clear cell renal cell carcinoma (ccRCC; cohort B)." (PMID 38920407, 2024).
Fanconi anemia (1 paper, 2024). Fanconi anemia (FA) is a hereditary DNA repair disorder characterized by progressive pancytopenia with bone marrow failure, variable congenital malformations and predisposition to develop hematological or solid tumors.
malignant pleural mesothelioma (1 paper, 2025). A malignant neoplasm that arises from mesothelial cells in the pleura and shows a diffuse growth pattern. "In a kinome, CRISPR‐Cas9 knockout screen in which kinases in malignant pleural mesothelioma (MPM) cancer cells were targeted WEE1, AURKA, MPP3, MAP3K12, DGKD and SPEG could be identified as candidate genes." (PMID 40242936, 2025).
metastatic cancer (1 paper, 2024). A carcinoma which has spread from the original site of growth to another anatomic site.
metastatic tumors (1 paper, 2012). "Whereas only 20% of the nevi displayed Wee1 expression in ≥10% of the tumor cells, this was the case for 42% of the primary- and 70% of the metastatic tumors." (PMID 22719872, 2012).
ovarian endometriosis (1 paper, 2021). A non-neoplastic disorder characterized by the growth of endometrial tissue in the ovaries. "Interestingly, WEE1 was recently identified as a differentially upregulated gene in the oocytes of ovarian endometriosis patients." (PMID 34686198, 2021).
pediatric tumors (1 paper, 2026). "Since previous studies have shown an ambiguous relation between WEE1 expression and adavosertib sensitivity in different cancer types, we strengthened our analysis using a validated signature reflecting adavosertib sensitivity for pediatric tumors." (PMID 41585496, 2026).
pilocytic astrocytoma (1 paper, 2014). Pilocytic astrocytoma is a rare subtype of low-grade glioma of the central nervous system characterized by a well circumscribed, often cystic, brain tumor with a discrete mural nodule and long, hair-like projections that extend from the neoplastic astrocytes. "Interestingly WEE1 was also expressed in the low-grade pilocytic astrocytoma (PA) in which there is very little proliferation." (PMID 24661910, 2014).
pituitary adenomas (1 paper, 2019). "The expression of Wee1 is decreased in pituitary adenomas and is regulated by miRs." (PMID 31165412, 2019).
prostate adenocarcinoma (1 paper, 2023). "WEE1 was reported to be differentially upregulated in NEPC tumors compared to androgen-sensitive prostate adenocarcinomas." (PMID 37987002, 2023).
renal tumours (1 paper, 2023). "We have previously identified an evolutionarily conserved synthetic lethality between loss of SETD2 and WEE1 inactivation, and that renal tumours with loss of SETD2 or H3K36me3 can be specifically targeted with WEE1 inhibition, an observation that has been taken into clinical trials." (PMID 37528416, 2023).
seminoma (1 paper, 2020). A radiosensitive malignant germ cell tumor found in the testis (especially undescended), and extragonadal sites (anterior mediastinum and pineal gland). "Both WEE1 and BRCA1 showed higher expression in seminoma compared to non‐seminoma samples according to the TCGA database, and the expression of BRCA1 was significantly correlated with TFAP2C." (PMID 32857912, 2020).
type I diabetes (1 paper, 2022). "LINC02086- hsa-miR-17-5p- MAPK9/WEE1 and LINC00960-hsa-miR-107-INSIG1, in association with the type I diabetes." (PMID 36440209, 2022).
urothelial carcinoma (1 paper, 2023). A malignant neoplasm derived from the transitional epithelium of the urinary tract (urinary bladder, ureter, urethra, or renal pelvis). "While the application of ATR inhibitors in urothelial carcinoma is still in its early stages of research, a potential new therapeutic approach involves combining Wee1 and ATR inhibition with conventional platinum-based chemotherapy." (PMID 37296592, 2023).
vulvar tumors (1 paper, 2013). "In the present study we analyzed the expression of Wee1 in a panel of 297 vulvar tumors by immunohistochemistry." (PMID 23767999, 2013).
cancer (994 papers, 2003 to 2026). A tumor composed of atypical neoplastic, often pleomorphic cells that invade other tissues. "For example, increased activation of checkpoint proteins such as CHK1 and WEE1, which mediate G2/M arrest, is linked to cancer radioresistance, and inhibitors have been proposed to enhance radiosensitivity." (PMID 40650150, 2025). "LKB1-deficient cancer cells are vulnerable to WEE1 inhibition, as the added stress overwhelms the cells’ capacity to maintain genomic integrity and hence leading to cell death." (PMID 40565165, 2025). "This oral Wee1 inhibitor has shown promise in treating advanced solid tumors by inducing premature mitosis and causing cancer cell apoptosis through DNA damage." (PMID 39204153, 2024). "Although not much is known about WEE1 regulatory activity in postmitotic differentiated cells such as neurons, studies from the cancer field indicate that WEE1 activity is closely linked to AKT and GSK3." (PMID 39125637, 2024). "A systematic review of the literature was conducted to analyze the association between WEE1 inhibition and cancer progression, including tumor advancement and drug resistance." (PMID 38231277, 2024). "Prior preclinical studies demonstrated a significant synthetic lethal effect with single-agent WEE1 inhibition in SETD2-deficient cancer models including ccRCC." (PMID 38920407, 2024). "Meanwhile, BMAL1/CLOCK knockdown induces the downregulation of the WEE1 gene, which encodes a checkpoint kinase essential for cancer cells’ survival and, consequently, leads to enhanced genome instability and apoptosis." (PMID 36937362, 2023). "Wee1 inhibition prolongs mitosis and makes cancer cells more susceptible to chemotherapy-induced mitotic catastrophe together with apoptosis induction." (PMID 38125947, 2023). "Loss of WEE1 activity is synthetic lethal with diminished histone H3K36me3, and thus cancers with low levels of H3K36me3 benefit from WEE1 inhibition." (PMID 35708734, 2022).